LINC00302 (long independently transcribed non-coding RNA 302)
Synonyms: XP33; C1orf46; NCRNA00302
Gene: Long non-coding RNA gene on chromosome 1 (152,655,453 to 152,656,806, forward strand). Ensembl gene ENSG00000304384.
Diseases named in the same sentence as LINC00302 in open-access papers:
LINC00302 is named in the same sentence as 1 disease in open-access papers, as found by Europe PMC text mining. Sharing a sentence is not in itself a finding about the gene and the disease.
LINC00302 shares sentences with these, for which no sentence is quoted: psoriasis (1 paper).